LARP4B (La ribonucleoprotein 4B)
Description:
Stimulates mRNA translation.
Synonyms: KIAA0217; LARP5
Tractability: PROTAC: ubiquitination databases record sites on it; its protein half-life has been measured.
Gene: Protein-coding gene on chromosome 10 (806,915 to 931,821, reverse strand). Ensembl gene ENSG00000107929.
Subcellular location: Cytoplasm, cytosol
Subcellular location (Human Protein Atlas): Cytosol
Gene Ontology:
Molecular function: mRNA 3'-UTR binding; protein binding; RNA binding; nucleic acid binding
Biological process: positive regulation of 3'-UTR-mediated mRNA stabilization; positive regulation of translation
Cellular component: cytoplasmic stress granule; cytosol; membrane
Genetic constraint (gnomAD): Loss-of-function variants: 11 observed, 62.93 expected, observed/expected ratio (o/e) 0.17, 90% interval 0.11 to 0.29. The upper end of that interval is the gene's LOEUF score, 0.29, which puts it in group 1 of 6, group 1 being the genes least tolerant of losing a copy. Missense variants: 657 observed, 812.24 expected, observed/expected ratio (o/e) 0.81, 90% interval 0.76 to 0.86. Synonymous variants: 312 observed, 322.04 expected, observed/expected ratio (o/e) 0.97, 90% interval 0.88 to 1.06.
Homologues: Orthologues: macaque LARP4B (96% identical), chimpanzee LARP4B (95% identical), guinea pig LARP4B (88% identical), rat Larp4b (85% identical), mouse Larp4b (85% identical), dog LARP4B (81% identical), tropical clawed frog larp4b (67% identical), zebrafish larp4b (48% identical), Drosophila melanogaster Larp4B (32% identical), Caenorhabditis elegans larp-5 (24% identical), Drosophila melanogaster larp (14% identical), Caenorhabditis elegans larp-1 (10% identical). Paralogues in human: LARP4 (36% identical), LARP1 (18% identical), LARP1B (17% identical), LARP6 (10% identical), LARP7 (10% identical), SSB (8% identical).
Diseases named in the same sentence as LARP4B in open-access papers:
LARP4B is named in the same sentence as 17 diseases in open-access papers, as found by Europe PMC text mining. Sharing a sentence is not in itself a finding about the gene and the disease. The quoted sentences say what the papers report.
glioma (7 papers, 2018 to 2024). A benign or malignant brain and spinal cord tumor that arises from glial cells (astrocytes, oligodendrocytes, ependymal cells). "In summary, LARP4B is a tumor-suppressor gene of glioma; the potential mechanisms involved, however, remain to be probed further." (PMID 36552760, 2022). "LARP4B expression was reported to be consistently decreased in human glioma stem cells and cell lines compared with normal neural stem cells." (PMID 36552760, 2022). "Our work illustrated this at the molecular level as BRCA1’s expression was significantly increased in glioma cells, while the expression of LARP4B was decreased." (PMID 34482648, 2021). "Overexpression of LARP4B in glioma cell lines strongly inhibited proliferation by inducing mitotic arrest and apoptosis." (PMID 29844869, 2018). "LARP4B expression was consistently decreased in human glioma stem cells and cell lines compared with normal neural stem cells." (PMID 29844869, 2018). "Interestingly, there were also reports of LARP4B helping to predict prognosis and immunotherapy in glioma patients." (PMID 36552760, 2022). "The involvement of LARP4B has been documented in many cancer processes, including medulloblastoma, malignant peripheral nerve sheath tumors, colorectal cancer, pancreatic cancer, and glioma." (PMID 31772683, 2019). "LARP4B, a RNA binding protein, is a candidate tumor suppressor gene in glioma." (PMID 29844869, 2018). "More experimental studies of LARP4B and ATP6AP1 in glioma are urgently needed to clarify their specific functions and potential mechanisms." (PMID 36552760, 2022). "In addition, we explored the proteins expressed by REEP6, LARP4B, CWC27, GOLGA2, ATP6AP1 and ERO1B in glioma patients through the HPA database, and REEP6, LARP4B, GOLGA2 and ATP6AP1 showed higher staining intensity in glioma than in normal brain tissue." (PMID 36552760, 2022).
liver cancer (2 papers, 2019 to 2025). An epithelial or non-epithelial malignant neoplasm that arises from the liver. "As far as we know, this is the first study to examine the diagnostic and prognostic values of LARP4B expression in liver cancer." (PMID 31772683, 2019). "A multivariate Cox model suggested that a high LARP4B expression was a potential independent risk factor for relapse-free survival in liver cancer patients (95% CI 1–2.13, P = 0.048, HR = 1.46)." (PMID 31772683, 2019). "In this study, we found that overexpressed LARP4B was associated with a poor prognosis in liver cancer patients, which may be attributable to the different functions of LARP4B in different tissues." (PMID 31772683, 2019). "The univariate/multivariate Cox regression model indicated that high LARP4B expression may be an independent risk factor for the prognosis of liver cancer patients." (PMID 31772683, 2019). "Among the newly identified immunopeptidome-evidenced neoantigens, we highlight shared neoantigens in colon cancer derived from frameshift mutations in LARP4B, as well as a missense mutation, CTNNB1 T41A, a driver gene in liver cancer." (PMID 40672284, 2025). "Our results suggest that LARP4B has strong potential as a marker in the clinical detection of liver cancer patients." (PMID 31772683, 2019). "The LARP4B expression level and clinical features of the TCGA liver cancer cohort include gender, age, histologic type and grade, sample type, T/N/M classification, radiation therapy, residual tumor, vital status, stage, and relapse." (PMID 31772683, 2019). "In this study, we have applied our extensive experience in the exploration of novel biomarkers to identify a biomarker, LARP4B, for the diagnosis and prognosis of patients with liver cancer." (PMID 31772683, 2019). "Subgroup analysis showed that LARP4B expression had a prognostic value in liver cancer patients who were T4 (P = 0.049), male (P = 0.014), stage III/IV (P = 0.037), G1/G2 (P = 0.022), and older (P = 0.024)." (PMID 31772683, 2019). "The expression of LARP4B was clearly related to age (P = 0.0274), gender (P = 0.0256), vital status (P = 0.0301), and histologic grade (P = 0.0003) of liver cancer patients." (PMID 31772683, 2019). "Chi-squared testing was used to assess clinical relevance, ROC curves were used to estimate diagnostic capability, and overall/relapse-free survival analyses were conducted to examine the impact of LARP4B on patients with liver cancer." (PMID 31772683, 2019). "In this investigation of LARP4B in the prognosis and diagnosis of liver cancer, we identified high LARP4B expression as a potential independent biomarker for negative prognosis." (PMID 31772683, 2019). "The Cancer Genome Atlas (TCGA) database was searched to detect LARP4B gene expression in liver cancer." (PMID 31772683, 2019). "Survival analysis showed that liver cancer patients with high LARP4B expression had shorter overall/relapse-free survival." (PMID 31772683, 2019). "Subgroup analysis showed that LARP4B expression had significant prognostic value in liver cancer patients who were older (P = 0.0049), T3 (P = 0.012), G1/G2 (P = 0.016), male (P = 0.01), and R0 (P = 0.013)." (PMID 31772683, 2019). "Boxplots showed higher LARP4B mRNA expression in liver cancer tissues compared with normal liver tissues (P = 4e‐13)." (PMID 31772683, 2019). "To assess the potential clinical role of LARP4B in liver cancer, we probed TCGA database for the mRNA expression of LARP4B in liver cancer patients." (PMID 31772683, 2019). "LARP4B mRNA was highly expressed in liver cancer tissues and was correlated with survival status." (PMID 31772683, 2019). "We aimed to explore the role of LARP4B in the diagnosis and prognosis of liver cancer." (PMID 31772683, 2019). "Additionally, we carried out gene set enrichment analysis (GSEA) to identify LARP4B-related signaling pathways in liver cancer." (PMID 31772683, 2019).
liver cancer (continued). "LARP4B is a potential independent biomarker for diagnosis and prognosis in liver cancer patients." (PMID 31772683, 2019). "Therefore, it is necessary to further explore the role of LARP4B in liver cancer." (PMID 31772683, 2019). "No such relationship between LARP4B and prognosis has been found in liver cancer." (PMID 31772683, 2019).
prostate carcinoma (2 papers, 2020 to 2022). A carcinoma that arises from epithelial cells of the prostate gland. "Even the combination of the five genes, including LARP4B, PLEKHF2, SMC4, SLC45A3 and NO6632,39,44,45,48,51, whose clinical relevance and prognostic implications were observed in prostate cancer, had very limited prediction strength for BCR and RFS (not reported in the Results section)." (PMID 35732666, 2022).
brain tumors (1 paper, 2018). "LARP4B and DMBT1 have already been reported as deleted in brain tumors." (PMID 29844869, 2018).
glioblastoma (1 paper, 2022). The most malignant astrocytic tumor (WHO grade IV). "The heterozygous deletion of LARP4B was detected in nearly 80% of glioblastomas in the TCGA database, which was associated with poor patient survival." (PMID 36552760, 2022).
hepatocellular carcinoma (1 paper, 2024). A malignant tumor that arises from hepatocytes. "However, the role of LARP4B and its underlying mechanisms in the progression of hepatocellular carcinoma (HCC) remain largely unclear." (PMID 38693111, 2024).
leukemia (1 paper, 2019). A malignant (clonal) hematologic disorder, involving hematopoietic stem cells and characterized by the presence of primitive or atypical myeloid or lymphoid cells in the bone marrow and the blood. "However, Mattijssen and Maraia found that LARP4B participated in the regulation of TNF-alpha-TTP as its functional activity in MLL-AF9 leukemia stem cells." (PMID 31772683, 2019).
osteosarcoma (1 paper, 2024). A usually aggressive malignant bone-forming mesenchymal neoplasm, predominantly affecting adolescents and young adults. "LARP4A and LARP4B are highly expressed in OS tissue and the depletion of LARP4A and LARP4B in MG63, osteosarcoma cell line, reduces the formation of lung metastatic foci, indicating a pivotal role for these proteins in the promotion of metastatic colonization." (PMID 38966428, 2024).
stomach adenocarcinoma (1 paper, 2017). "Further analysis revealed an unexpected enrichment of NMD-elicit mutations in LARP4B (22/54 compared) and EIF5B (12/54) in hypermutated stomach adenocarcinoma cases." (PMID 28649990, 2017).
cancer (10 papers, 2015 to 2024). A tumor composed of atypical neoplastic, often pleomorphic cells that invade other tissues. "It is conceivable that NMD-mediated hypofunction of LARP4B or EIF5B permits the hypermutated cancer cells to cope with a high mutation load by delaying translation." (PMID 28649990, 2017). "This revealed that 4 out of 10 cancers with MSI had mutations that would induce PTCs in LARP4B and three of those mutations occurred at the same site mentioned in TCGA data (chr10:890939-T, hg19)." (PMID 28649990, 2017). "These sequencing data indicate that LARP4B is involved in cellular processes related to cancer and malignant transformation." (PMID 38693111, 2024). "LARP4 and LARP4B exhibit similar overall architectures but with different functionalities in cancer and other processes, verified by direct comparisons." (PMID 39554137, 2024). "The RNA-binding protein la ribonucleoprotein 4B (LARP4B) has a la motif (lam) that is important in the process of cancer." (PMID 31772683, 2019). "It is possible that LARP4B participates in the progression of different cancers through multiple signaling pathways." (PMID 31772683, 2019). "Together with other studies on the functions of LARP4B, we have contributed to a better understanding of the role of LARP4B and expanded the possibilities for more precise diagnosis and prognosis in cancer." (PMID 31772683, 2019). "LARP6, as well as post-transcriptionally driving collagen synthesis which is an essential cytoskeletal component of the migrating cancer cell, also regulates gene transcription and LARP4b regulates the transcription factor C/EBPα." (PMID 26501340, 2015). "Emerging evidence has shown that LARPs are dysregulated in cancer and play key roles in cancer progression; however, the exact role of LARP4B in cancer development remains unclear." (PMID 38693111, 2024). "There has been no published association between LARP4b and cancer." (PMID 26501340, 2015). "Our data demonstrated mRNA PAT net lengthening activity for two other La module proteins, LARP4B and LARP1, the latter of which is a regulator of ribosome biogenesis and a pro-cancer protein." (PMID 28895529, 2017). "Furthermore, rs141536087 is an eQTL for LARP4B in the Mayo set (p-value = 4.5e-15) but not in the two cancer sets (p-value = 0.41 for FH and 0.63 for TCGA)." (PMID 32226005, 2020).
tumor (10 papers, 2017 to 2024). "A methylated RNA immunoprecipitation (MeRIP) assay revealed increased m6A levels in LARP4B mRNA in HCC tumor tissues compared to normal tissues." (PMID 38693111, 2024). "Five tumor suppressor genes have variants (RNF43 G659fs, NPM1 W288fs, RPL22 K15fs, ACVR2A K437fs, LARP4B T163fs) that occur in over 5% of samples in at least one cohort." (PMID 34214079, 2021). "A univariate Cox model revealed that residual tumor, stage, T classification, and LARP4B expression represented potential survival-related variables." (PMID 31772683, 2019). "A univariate Cox model showed that residual tumor, stage, T classification, and LARP4B expression represented potential relapse-free survival-related variables." (PMID 31772683, 2019). "Additionally, the limiting dilution assay showed that the probability of tumor formation was lower in the LARP4B knockdown group than in the control group, suggesting that LARP4B knockdown reduces the tumor initiation capacity of Huh7 cells." (PMID 38693111, 2024). "Furthermore, LARP4B inhibition resulted in reduced tumor growth and enhanced tumor sensitivity during treatment with a medium dose of sorafenib (30 mg/kg)." (PMID 38693111, 2024). "The third CpG site (cg01503450) is situated in the promoter region of LARP4B, a gene involved in RNA translation, and could be a tumor suppressor gene." (PMID 35751095, 2022). "In addition, IHC staining showed that LARP4B overexpression increased Ki67, CD31, and CD34 expression in tumor tissues, whereas LARP4B knockdown decreased its expression." (PMID 38693111, 2024).
LARP4B also shares sentences with these, for which no sentence is quoted: bladder cancer (1 paper); colon cancer (1); colorectal cancer (1); malignant peripheral nerve sheath tumor (1); medulloblastoma (1); pancreatic cancer (1).